ZNF207 (zinc finger protein 207)
Description:
Kinetochore- and microtubule-binding protein that plays a key role in spindle assembly. ZNF207/BuGZ is mainly composed of disordered low-complexity regions and undergoes phase transition or coacervation to form temperature-dependent liquid droplets. Coacervation promotes microtubule bundling and concentrates tubulin, promoting microtubule polymerization and assembly of spindle and spindle matrix by concentrating its building blocks. Also acts as a regulator of mitotic chromosome alignment by mediating the stability and kinetochore loading of BUB3. Mechanisms by which BUB3 is protected are unclear: according to a first report, ZNF207/BuGZ may act by blocking ubiquitination and proteasomal degradation of BUB3. According to another report, the stabilization is independent of the proteasome.
Synonyms: BuGZ; hBuGZ
Tractability: PROTAC: ubiquitination databases record sites on it; its protein half-life has been measured.
Gene: Protein-coding gene on chromosome 17 (32,350,122 to 32,381,885, forward strand). Ensembl gene ENSG00000010244.
Subcellular location: Nucleus; Chromosome, centromere, kinetochore; Cytoplasm, cytoskeleton, spindle
Subcellular location (Human Protein Atlas): Nucleoplasm
Gene Ontology:
Molecular function: microtubule binding; protein binding; RNA binding; heparin binding
Biological process: attachment of spindle microtubules to kinetochore; mitotic sister chromatid segregation; mitotic spindle assembly; mitotic spindle assembly checkpoint signaling; protein stabilization; regulation of chromosome segregation; microtubule bundle formation; microtubule polymerization
Cellular component: kinetochore; nucleoplasm; nucleus; spindle matrix; spindle
Genetic constraint (gnomAD): Loss-of-function variants: 24 observed, 56.49 expected, observed/expected ratio (o/e) 0.42, 90% interval 0.31 to 0.6. The upper end of that interval is the gene's LOEUF score, 0.6, which puts it in group 2 of 6, group 1 being the genes least tolerant of losing a copy. Missense variants: 452 observed, 639 expected, observed/expected ratio (o/e) 0.71, 90% interval 0.65 to 0.76. Synonymous variants: 236 observed, 195.46 expected, observed/expected ratio (o/e) 1.21, 90% interval 1.09 to 1.35.
Homologues: Orthologues: macaque ZNF207 (100% identical), rabbit ZNF207 (100% identical), guinea pig ZNF207 (99% identical), rat Zfp207 (99% identical), mouse Zfp207 (99% identical), chimpanzee ZNF207 (97% identical), pig ZNF207 (97% identical), tropical clawed frog znf207 (79% identical), zebrafish znf207a (64% identical), zebrafish znf207b (61% identical), Caenorhabditis elegans znf-207 (30% identical).
Diseases named in the same sentence as ZNF207 in open-access papers:
ZNF207 is named in the same sentence as 16 diseases in open-access papers, as found by Europe PMC text mining. Sharing a sentence is not in itself a finding about the gene and the disease. The quoted sentences say what the papers report.
liver cancer (2 papers, 2024). An epithelial or non-epithelial malignant neoplasm that arises from the liver. "Then software analysis enabled us to determine that the AS patterns of ZNF207 are altered in liver cancer tissues when hnRNPA1 expression is reduced." (PMID 39834948, 2024).
ovarian carcinoma (2 papers, 2022 to 2025). A malignant neoplasm originating from the surface ovarian epithelium.
acute myeloid leukemia (1 paper, 2022). Acute myeloid leukemia (AML) is a group of neoplasms arising from precursor cells committed to the myeloid cell-line differentiation. "Among these, the mRNA expression of BUB3, DHX9, PRMT1, THOC4, THOC7, U2AF1, and ZNF207 (BUGZ) were found to increase in several primary tumors compared to healthy tissues, while SRSF1 (ASF/SF2) was downregulated in most cancers (except for acute myeloid leukemia—LAML)." (PMID 36553448, 2022).
progeria (1 paper, 2025). "As proof-of-concept, CRASP-Seq analysis of an LMNA cryptic splicing event linked to progeria uncovered ZNF207, primarily known for mitotic spindle assembly, as a regulator of progerin splicing." (PMID 40568141, 2025). "To determine whether depleting ZNF207 could rescue molecular phenotypes associated with progeria, we assessed its impact on hallmark disease features in immortalized fibroblasts." (PMID 40568141, 2025).
cancer (14 papers, 2016 to 2025). A tumor composed of atypical neoplastic, often pleomorphic cells that invade other tissues. "We found that specific clinical traits, such as cutaneous and neurodevelopmental abnormalities or cancer susceptibility, could be associated with the position effect of ZNF207 and RHOT1 downregulation, respectively." (PMID 38874808, 2024). "To investigate, we knocked down ZNF207 and assessed whether it causes defects in spindle formation as reported in cancer cells." (PMID 30349051, 2018). "Studies have explored immunosuppressive targets in HCC by integrating cancer-immune cycle scores with bioinformatics, identifying ZNF207 in this context." (PMID 39834948, 2024). "In differentiated cells and cancer cells, isoform B of ZNF207 interacts with spindle assembly checkpoint (SAC) proteins to regulate mitotic chromosome alignment." (PMID 30349051, 2018). "ZNF207 has been shown to influence pre‐mRNA splicing in cancer cells." (PMID 35037361, 2022). "Among the list of co-expressed features of interest, both RARA (retinoic acid receptor alpha) and RXRA (retinoid X receptor alpha) are identified as strong negative correlates, whereas ZNF207, an early developmental factor linked with pluripotency factors, is a strong positive correlate in cancer." (PMID 37894362, 2023). "The role of ZNF207 in cancer, particularly in HCC, underscores its importance in the field of oncology, aligning with the broader research on zinc finger proteins in cancer." (PMID 39834948, 2024). "Collectively, the splicing modulation of VPS39, ZNF207, and TBC1D4 in curcumin-treated HNC cells provides the basis for future investigation of the role of cancer-specific isoforms of these genes in tumorigenesis." (PMID 31675998, 2019).
tumor (3 papers, 2015 to 2024). "Consistent with the data from the RNAseq analysis, three HER2 fusion genes—ZNF207 (exon 1–2)/HER2 (exon 18–30), MDK (exon 1–4)/HER2 (exon 11–30), and NOS2 (exon 1–2)/HER2 (exon 2–30)—were further confirmed in these tumor DNA samples." (PMID 25889497, 2015).
ZNF207 also shares sentences with these, for which no sentence is quoted: glioblastoma (3 papers); breast carcinoma (2); autoimmune disease (1); Cirrhosis (1); colon cancer (1); hepatocellular carcinoma (1); leukemia (1); lung adenocarcinoma (1); non-small cell lung carcinoma (1); seminoma (1).